RN7SKP75 (RN7SK pseudogene 75)
Gene: Miscellaneous RNA gene on chromosome 7 (71,685,452 to 71,685,747, reverse strand). Ensembl gene ENSG00000199940.
Homologues: Orthologues: chimpanzee 7SK (99% identical). Paralogues in human: RN7SKP9 (79% identical), 7SK (78% identical), RN7SKP79 (78% identical), RN7SKP217 (78% identical), RN7SKP255 (78% identical), RN7SKP189 (77% identical), RN7SKP176 (77% identical), RN7SKP87 (77% identical), RN7SKP162 (76% identical), RN7SKP180 (76% identical), RN7SKP203 (76% identical), RN7SKP90 (76% identical), and 284 more.